CXCR4 (C-X-C motif chemokine receptor 4)
Diseases named in the same sentence as CXCR4 in open-access papers (continued):
Sharing a sentence is not in itself a finding about the gene and the disease.
tumor (continued). "Our study highlights the heterogeneity of the G3 neoplasms, and describes significant differences in SSTR1 and CXCR4 expression." (PMID 26259237, 2015). "Meanwhile, overexpression of miR-222 inhibited TAM chemotaxis, and miR-222 in TAMs inhibited 4T1 tumor growth by targeting CXCL12 and inhibiting CXCR4." (PMID 26689540, 2015). "Advanced TNM stage, positive resection margins, poor tumor differentiation and EGFR/CXCR4 coexpression were independent unfavorable prognostic factors for both DFS and OS." (PMID 25679210, 2015). "In this study, we found that the expressions of HIF-1α, CXCR4 and SDF-1α were co-localized in the peripheral region of necrotic tumor tissues, which were relatively hypoxic due to reduced blood flow." (PMID 25843954, 2015). "Interaction between the chemokine receptor CXCR4 and its ligand, SDF-1α, have also been shown to be involved in metastasis of several tumours 3–7." (PMID 25753200, 2015). "Epigenetic mechanisms like demethylation of CXCR4 and hypermethylation of CXCL12 and ESR1 are a characteristic of tumor stage, size, metastasis, and poor overall survival." (PMID 25814785, 2015). "These cells promote tumor growth and angiogenesis via secretion of stromal-cell derived factor 1 (SDF-1), which binds to CXCR4 expressed by tumor cells." (PMID 26694366, 2015). "We evaluated the adjunction of a CXCR4 antagonist on GBM explants isolated from three patients and demonstrated a greater anti-tumor effect with the combination of AMD3100 and radiotherapy plus temozolomide versus radiotherapy and temozolomide alone." (PMID 25860928, 2015). "High expression of CXCR4 and CXCL12 has been observed in various carcinomas, resulting in increased cell migration and tumor angiogenesis." (PMID 26560447, 2015). "With respect to the detection of CXCR4 expression by means of IHC, the specificity of the rabbit monoclonal antibody UMB-2 has been shown in different tumor entities." (PMID 25671300, 2015). "In cancer, CXCR4 overexpression and receptor activation by SDF-1 binding are key triggers for tumor growth and progression, invasiveness, and metastasis." (PMID 25736399, 2015). "In this condition we observed the failure of ECFCs to home into tumor mass, confirming the involvment of the SDF1/CXCR4 system in the in vivo recruitment of ECFCs." (PMID 25003596, 2014). "To determine the molecular basis of how TSPY1 enhanced invasive abilities of HCC cells, we next examined two invasion-related genes CXC chemokine receptor 4 (CXCR4) and hypoxia inducible factor-1 (HIF-1) that are known to play major role in tumor metastasis." (PMID 24586606, 2014). "Seeking reliable markers to predict chemotherapeutic efficacy in advanced esophagogastric cancer, tumour tissues from 72 patients from the collective of the FLO vs. FLP phase III study of the AIO were tested for expression of VEGFR-3 and CXCR4." (PMID 24981311, 2014). "Together, these data indicate that CXCR4 antagonism reduces the GBM TIC fraction through direct action, requiring drug permeation into tumor tissue." (PMID 25238146, 2014). "Using a recombinant lentiviral RNA interference vector of the CXCR4 gene in highly aggressive (Tca8113 and SCC-9) tumor cells, significant inhibition of the proliferation of both cell lines in vitro and in vivo was shown." (PMID 24647809, 2014). "Tumour tissues were stained via immunohistochemistry for VEGFR-3 and CXCR4 expression and results were evaluated by two independent, blinded investigators." (PMID 24981311, 2014). "CXCR4 and CXCL12 play an essential role in tumor growth, metastasis, and cancer cell-microenvironment interaction." (PMID 25471741, 2014). "The expression of chemo-attractant molecules and their receptors (such as CXCL12-SDF1/CXCR4 and VEGF/VEGFRs) induces tumor cell dissemination from primitive tumor sites to metastatic niches." (PMID 24629239, 2014). "Recovery of the tumor microvasculature is mediated, in part, by CXCL12 and CXCR4, but the role of receptor CXCR7 remains controversial." (PMID 25084358, 2014).
tumor (continued). "Other than CXCR4, we and other groups have also shown the involvement of CXCR5 and CCR9 in survival and metastasis of tumor cells in different malignancies." (PMID 25296976, 2014). "While both CXCR4 and CXCR7 are expressed by human MSC, only CXCR4 mediates their migration in response to tumor cells as shown in gene silencing experiments, and knockdown of CXCR7 had a minimal effect on migration of MSC." (PMID 24757448, 2014). "Peptide-based CXCR4 antagonists (TC14012, TZ14001 and TN14003), derived from T140, demonstrated, in preclinical studies, ability to prevent tumor growth and metastasis in animal models of breast, head, and neck carcinoma." (PMID 24904289, 2014). "In particular, CXCL12, through its receptors CXCR4 and CXCR7, affects tumor progression by controlling cancer cell survival, proliferation and migration, and, indirectly, via angiogenesis or recruiting immune cells." (PMID 24904289, 2014). "We showed that AMD3100 or AMD3465, related CXCR4 antagonists, inhibit the growth of intracranial GBM xenograft models by decreased proliferation and increased apoptosis of tumor cells." (PMID 25238146, 2014). "CXCR4 controls chemotactic and invasive behavior (in vivo motility and intravasation) in response to CXCL12, whereas CXCR7 enhances primary tumor growth and angiogenesis but decreases in vivo invasion, intravasation, and metastasis formation." (PMID 25165728, 2014). "We therefore examined and compared the effect of combined chemotherapy with oxaliplatin/leucovorin/5-FU (FLO) versus cisplatin/leucovorin/5-FU (FLP) in patients with advanced esophagogastric cancer in relation to tumour VEGFR-3 and CXCR4 expression." (PMID 24981311, 2014). "It was shown that a synthetic antagonist of CXCR4, d-Arg3FC131, is able to inhibit the growth of GH3 tumor cells and trigger apoptosis both in vitro and in mice xenografts." (PMID 25484899, 2014). "Further research has emphasized the key role of CXCR4 in tumor cell malignancy; the activation of CXCR4 by CXCL12 has been shown to induce the migration, invasion and angiogenesis of tumor cells." (PMID 25268356, 2014). "Thus, CXCR4 expression on CTCs could mediate homing of tumor cells to lymph nodes." (PMID 24709997, 2014). "Thus, SDF-1/CXCR-4 may contribute greatly to the formation of tumor microenvironment and niche." (PMID 24587996, 2014). "They observed decreased expression of CXCR4 in patients with higher FIGO stages, deep myometrial invasion, lymph node and adnexal metastases, and more aggressive phenotype of the tumor." (PMID 24416254, 2014). "54% and 36% of the examined tumour tissues showed strong positive expression of VEGFR-3 and CXCR4 respectively." (PMID 24981311, 2014). "In this study we assessed the effect of inhibition of the CXCL12/CXCR4 pathway by a novel CXCR4 antagonist, CTCE-9908 on in vitro cell proliferation and invasion, and in vivo orthotopic tumor growth, metastasis, and angiogenesis of PC cells." (PMID 24472670, 2014). "Studies in OS mouse models of experimental metastasis, revealed by intravenous injections of tumor cells, indeed demonstrated the relevance of the CXCL12/CXCR4 axis in OS metastasis." (PMID 24390633, 2014). "Beside direct CXCR4-dependent activation of ERK1/2, transactivation of tyrosine kinase receptors is currently a relevant mechanism in tumor cell responses." (PMID 25484899, 2014). "Tumor cells secrete large quantities of SDF-1, and MSCs express the SDF-1 receptor CXC chemokine receptor 4 (CXCR4)." (PMID 24502410, 2014). "Some of these hypoxia-responsive genes, such as CXCR4 and VEGF, are closely correlated to the regulation of tumor tropism of NSCs." (PMID 24864258, 2014). "In GBM, CXCR4 and CXCL12 are overexpressed in tumor tissue when compared with normal adjacent parenchyma, and their expression level is correlated with tumor grade and poor prognosis." (PMID 24904289, 2014).
tumor (continued). "Of these overexpressed genes, 5 (CXCR4, CXCL12, MMP2, MMP9 and MMP13) were selected on the basis of their strong correlation with tumor metastasis and were validated by qPCR." (PMID 24179538, 2013). "The molecular mechanisms through which miR-146a contributes to tumor development are unclear but they seem to be related to the ability of this miRNA to target some mRNAs, such as TRAF6, IRAK1, CXCR4, NF-κB and EGFR." (PMID 24376808, 2013). "The present study is the first to detect the expression of CCR7, CXCR4 and VEGF-C in tumor tissues using real-time RT-PCR and immunohistochemistry assays in a large series of human PDAC specimens." (PMID 23761820, 2013). "It is possible that CCR7, CXCR4 and VEGF-C interact with each other in the process of the metastatic spread of tumor cells to distant regional lymph nodes." (PMID 23761820, 2013). "In contrast, CXCR4, which plays a pivotal role in the metastasis of NSCLC, has been reported to show an increased expression in tumor tissues." (PMID 23451142, 2013). "First and most importantly, the promiscuity of CXCR7 ligands and the widespread expression of CXCR4 and CXCR3 in tumor tissues makes the dissection of CXCR7-specific signaling particularly challenging." (PMID 23894550, 2013). "Akt1-induced CXCR4 expression is active in CXCL12-induced cellular invasion, tumor growth, and intraosseous tumor growth in murine model systems." (PMID 23902739, 2013). "Paclitaxel on the contrary, raises ALDH, CXCR4, and SDF-1 levels, and promotes metastatic spread (while reducing primary tumor volume) in the in vivo model we have used." (PMID 24278179, 2013). "Three (CD74, CXCR4, PLAGL2) of 7 human genes found in these tumor/hamster hybrid cells showed transcriptional activities in vivo or in vitro for years." (PMID 23667660, 2013). "Balkwill reviewed studies demonstrating that malignant cells from different types of cancer express CXCR4 and interact with its ligand, SDF-1, indicating the critical role that the SDF-1/CXCR4 pathway plays in tumor metastasis." (PMID 23987636, 2013). "The activation of CXCR4, a G protein-coupled receptor for CXCL12, induced tumor invasion and/or survival of cancer cells." (PMID 24330809, 2013). "We used bioluminescence from HeyA8-CXCR4-CBRN/Ar-CBC to analyze CXCR4 signaling in vivo and fluorescence imaging for eqFP650 to quantify tumor burden over time." (PMID 23372646, 2013). "Several reports have indicated that TPL can reduce the growth and metastasis of tumours in vivo and in vitro, via inhibition of heat shock protein 70 (HSP70), CXC chemokine receptor 4 (CXCR4), or uPAR." (PMID 23758884, 2013). "Condeelis and Pollard showed that there is direct communication between macrophages and tumor cells through receptor-ligand interactions, mainly EGFR-EGF and CXCR4-CSF-1." (PMID 23577028, 2013). "CXCR4 is the receptor of stromal cell-derived factor-1 (CXCL12/SDF-1α) and can also bind to MIF, and takes an important role in tumor progression and anti-tumor immunity." (PMID 23497377, 2013). "CXCR4, and its ligand CXCL12, regulates chemotactic migration and “homing” of tumor cells to a secondary organ/site, and facilitates tumor cell extravasation." (PMID 24069584, 2013). "This unexpected finding prompted a detailed immunohistochemical analysis of the auriculum cordis and of the lung for expression of endogenous CXCL12 as a chemo-attractant for CXCR4 and even more for CXCR4/CXCR7 co-expressing tumor cells." (PMID 24040160, 2013). "There is direct communication between macrophages and tumor cells importantly mediated by interactions between EGFR-CSF-1 and CXCR4-EGF." (PMID 23762835, 2013). "CXCR4, the upstream molecule of the PI3 kinase/Akt pathway, has been shown to directly or indirectly regulate tumor growth." (PMID 24094005, 2013). "In CE81T tumor-bearing mice, 1BB1 reduced tumor growth and downregulated TGF-β, cyclin B1, MMP-1, and CXCR4 expression in tumors." (PMID 24130695, 2013).
tumor (continued). "CXCR4 is one of the target genes of HIF-1α and it has been well documented that hypoxia-induced expression of CXCR4 in various tumor cells is regulated by the activation of HIF-1α, thereby promoting the aggressiveness of tumor." (PMID 23671625, 2013). "Functional characterization of CXCR4 and CXCR7 revealed diverse roles of both receptors in promoting tumor cell growth, migration, sphere formation, and tube formation in vitro and depended on the specific GBM line." (PMID 23555768, 2013). "CXCR4 and CXCL12 are one of the most well studied chemokine systems in tumor growth, metastasis, and angiogenesis." (PMID 23555768, 2013). "Expression rates increased with tumor grade for GLUT1, CAIX, and CXCR4 (all p < 0.001), but decreased for IGF1R (p < 0.001)." (PMID 24206539, 2013). "CXCR4 is the receptor of SDF1/CXCL12, and their interaction promotes increased tumor cell proliferation and survival." (PMID 23762835, 2013). "Increased tumor cell apoptosis and necrosis has also been observed following impairment of the CXCL12/CXCR4 axis." (PMID 24384839, 2013). "Herein, using cultured cells from PTEN intact, heterozygous, and knockout cells, we show that both CXCR4 and CXCL12 expression is higher in PTEN knockout cells, thus confirming the immunohistochemical tumor expression findings." (PMID 23902739, 2013). "The CXCR4-specific antagonist inhibits SDF-1-induced CXCR4/Akt signal transduction, and effectively suppresses tumor growth in the PC-3 xenograft model." (PMID 24137439, 2013). "Within the 32-gene signature, genes upregulated in the pSP include previously proposed pancreatic CSC markers (CXCR4, CD133) or play a role in multidrug resistance (ABCB1) and in pathways important in tumorigenesis and tumor progression." (PMID 24069258, 2013). "The present study focused on the biological relevance of CXCR7 in OS in interaction with the CXCR4/CXCL12 axis, reported to promote primary tumor growth and metastasis." (PMID 24040160, 2013). "Treatment of animals with AMD3100 abolished the effect of wounds on tumor growth, demonstrating that intact SDF-1α/CXCR4 signaling is necessary for wound-promoted tumor growth." (PMID 23593347, 2013). "As far as the malignant primary tumours CXCR expression, although we observed some variability in the intensity of the anti-CXCR4 immunoreaction, only occasionally we detected variation in the percentage of positive cells." (PMID 22417013, 2012). "Phenotypes underlying such clustering patterns showed that CTCs maintained higher expression than all tumor cell lines for FOXC1, KRT18, PTEN, NPTN, TGFß1, KRT8, ZEB2, and CXCR4." (PMID 22586443, 2012). "Among the chemokines involved in tumor metastasis, the CXCL12 (also known as SDF-1 or stromal-derived factor)/CXCR4 axis plays a critical role in stem cell migration." (PMID 22408433, 2012). "Here, we demonstrate positive correlations between CXCR4 expression levels in therapy-naïve EWS and tumor volume at diagnosis." (PMID 23249693, 2012). "The chemokine CXCL12, and its receptors CXCR4 and CXCR7 have been involved in tumor progression and dissemination." (PMID 22916293, 2012). "Cross-talking between SDF-1α/CXCR4 axis and VEGF pathway is proved to favor tumor progression as angiogenesis and migration are requisites to metastasis promotion." (PMID 23300882, 2012). "Whereas CXCR4 was predominantly expressed by tumor cells, CXCL12 was observed in both tumor and stromal areas." (PMID 23249693, 2012). "Administration of the specific small molecule CXCR4 antagonist AMD3100 to mice with intracranial glioblastoma effectively inhibited growth and increased apoptosis of the tumor cells." (PMID 22433180, 2012). "The anti-tumor effects of AMD3100 and AMD3465, competitive antagonists of CXCR4 activation also indicate that CXCL12 regulation of tumor growth involves activation of tumor cell CXCR4." (PMID 22427929, 2012).
tumor (continued). "We performed an in vitro chemotaxis assay with the chemokine ligands for CCR8 and CXCR4 (CCL1 and CXCL12) and observed these chemokines induced more efficient chemotaxis of tumor-infiltrating FoxP3+ T cells compared to their counterparts in lymph nodes." (PMID 22292042, 2012). "Conversely, molecules proposed to be direct mediators of lymphatic colonization include CCL21 and SDF-1 interacting with their tumor-expressed receptors, CCR7 and CXCR4, respectively." (PMID 22295241, 2012). "In contrast, several studies have highlighted the key role played by chemokines during metastasis, particularly among tumor cells that express chemokines receptors CXCR3 and CXCR4." (PMID 22927846, 2012). "In that context, CXCR7 has been clearly demonstrated to control cell migration in a zebrafish model, and to regulate migratory advantage provided by CXCR4 in CXCR4/CXCR7-expressing primary T cells and tumor cells." (PMID 22916293, 2012). "As CXCR4 is largely expressed in high grade NBs, co-expression of the two CXCL12 receptors in tumor tissues is then likely." (PMID 22916293, 2012). "Hitherto, our results indicate that the CXCR4/CXCL12 axis is frequently expressed in EWS and affects tumor progression and patient survival by promoting cell growth." (PMID 23249693, 2012). "Supporting the role of CXCR4 in tumor activities in SW1116 cells, we herein silenced CXCR4 signaling by transducing with pLKO.1-shRNA-CXCR4 and demonstrated that CXCR4 plays a critical role in cell growth, Matrigel adhesion and invasion." (PMID 23071744, 2012). "CXCR4 expression localized to the same areas as that of SDF-1, but seemed to be less abundant both at the tumor-bordering brain and the tumor core." (PMID 22539956, 2012). "Further investigations on how high expression of CXCR4 and EMT occur in this identified cancer stem cell subset are warranted to provide insights into our understanding of tumor biology." (PMID 22871210, 2012). "An association between metastasis status and a high prevalence of certain markers including CD44+/CD24−/low, ESA+, CD133+, C-X-C chemokine receptor type 4 (CXCR4)+ and PROCR+ in primary tumor cells was also found." (PMID 24977105, 2012). "CXCR4 is frequently overexpressed on tumor cells, and the SDF-1/CXCR4 axis is thought to play a role in promoting survival, angiogenesis, and metastasis." (PMID 22536253, 2012). "Tumor invasion is regulated by numerous NF-κB target gene products, including MMP-9, TIMP-1/2, PAL 2, CXCR4, interleukin-8 (IL-8), and other chemokines." (PMID 22776619, 2012). "CXCR4- and HER2-expression was observed in all tumor bearing-tissues, including primary tumor, liver, lung and lymph node metastases." (PMID 23082154, 2012). "At day 5 after tumor cell implantation, the tumors of animals pretreated with anti-c-Kit antibodies showed a significantly higher expression of VEGF and CXCR4 compared to controls (P < 0.05)." (PMID 21977032, 2012). "We also showed that K5 treatment markedly down-regulated CXCR4 expression both in LLC cells and LLC-grafted tumor tissues." (PMID 23300882, 2012). "High expression of CXCL12 was seen in only 20% of the tumours, suggesting a role for anti-CXCL12/CXCR4 therapy in the management of these patients." (PMID 22415233, 2012). "The inhibition of HER2 with trastuzumab on one hand leads to a significant reduction of primary tumor growth as well as a significant reduction of metastases and to significant changes in the expression levels of HER2 and CXCR4 in the primary tumor." (PMID 23082154, 2012). "Several groups found that CXCR4 and its ligand CXCL12 can promote tumour cell migration and invasion." (PMID 22253872, 2012). "The present study demonstrated that K5 can inhibit LLC tumor growth and metastasis by regulating HIF-1α and its downstream genes of VEGF and CXCR4." (PMID 23300882, 2012). "In the tumor microenvironment, HGF regulates the expression of c-Met and CXCR4 through autocrine or paracrine actions." (PMID 22242160, 2012).